KCNK10 (potassium two pore domain channel subfamily K member 10)
Description:
K(+) channel that conducts voltage-dependent outward rectifying currents upon membrane depolarization. Voltage sensing is coupled to K(+) electrochemical gradient in an 'ion flux gating' mode where outward but not inward ion flow opens the gate. Converts to voltage-independent 'leak' conductance mode upon stimulation by various stimuli including mechanical membrane stretch, acidic pH, heat and lipids. Homo- and heterodimerizes to form functional channels with distinct regulatory and gating properties. In trigeminal ganglia sensory neurons, the heterodimer of KCNK10/TREK-2 and KCNK18/TRESK inhibits neuronal firing and neurogenic inflammation by stabilizing the resting membrane potential at K(+) equilibrium potential as well as by regulating the threshold of action potentials and the spike frequency (By similarity). Permeable to other monovalent ions such as Rb(+) and Cs(+).
Synonyms: TREK2; K2p10.1; TREK-2; PPP1R97
Tractability: Small molecule: an approved drug acts on it; a structure with a bound ligand is known; a high-quality ligand is known; it belongs to a druggable protein family. Antibody: its Gene Ontology location is reachable by antibodies, with high confidence; UniProt places it where antibodies can reach, with medium confidence; UniProt predicts a signal peptide or a membrane-spanning region. PROTAC: ubiquitination databases record sites on it; a small molecule that binds it is known.
Target class: Two-pore domain potassium channel; Voltage-gated ion channel; Ion channel; Potassium channels
Gene: Protein-coding gene on chromosome 14 (88,180,103 to 88,326,907, reverse strand). Ensembl gene ENSG00000100433.
Subcellular location: Cell membrane
Pathways (Reactome):
Muscle contraction: Phase 4 - resting membrane potential
Neuronal System: TWIK related potassium channel (TREK)
Gene Ontology:
Molecular function: mechanosensitive potassium channel activity; outward rectifier potassium channel activity; potassium ion leak channel activity; potassium channel activity
Biological process: cellular response to arachidonate; signal transduction; potassium ion transmembrane transport
Cellular component: plasma membrane; membrane
Genetic constraint (gnomAD): Loss-of-function variants: 23 observed, 46.87 expected, observed/expected ratio (o/e) 0.49, 90% interval 0.35 to 0.69. The upper end of that interval is the gene's LOEUF score, 0.69, which puts it in group 2 of 6, group 1 being the genes least tolerant of losing a copy. Missense variants: 547 observed, 725.47 expected, observed/expected ratio (o/e) 0.75, 90% interval 0.7 to 0.81. Synonymous variants: 296 observed, 292.39 expected, observed/expected ratio (o/e) 1.01, 90% interval 0.92 to 1.12.
Homologues: Orthologues: macaque KCNK10 (99% identical), chimpanzee KCNK10 (99% identical), pig KCNK10 (95% identical), dog KCNK10 (95% identical), rabbit KCNK10 (94% identical), guinea pig KCNK10 (94% identical), mouse Kcnk10 (93% identical), rat Kcnk10 (93% identical), tropical clawed frog kcnk10 (80% identical), zebrafish kcnk10a (67% identical), zebrafish kcnk10b (63% identical), Drosophila melanogaster Ork1 (20% identical), and 12 more. Paralogues in human: KCNK2 (46% identical), KCNK4 (30% identical), KCNK16 (19% identical), KCNK5 (18% identical), KCNK17 (17% identical), KCNK1 (17% identical), KCNK12 (17% identical), KCNK6 (16% identical), KCNK3 (16% identical), KCNK13 (16% identical), KCNK9 (15% identical), KCNK15 (15% identical), and 2 more.
Diseases named in the same sentence as KCNK10 in open-access papers:
KCNK10 is named in the same sentence as 24 diseases in open-access papers, as found by Europe PMC text mining. Sharing a sentence is not in itself a finding about the gene and the disease. The quoted sentences say what the papers report.
epilepsy (2 papers, 2020 to 2022). A brain disorder characterized by episodes of abnormally increased neuronal discharge resulting in transient episodes of sensory or motor neurological dysfunction, or psychic dysfunction. "Mir187 (paired with the Interleukin 12 Receptor Subunit Beta Il12rb1) is associated with the regulation of the potassium channel KCNK10/TREK-2 in a rat epilepsy model." (PMID 32093602, 2020).
schizophrenia (2 papers, 2022 to 2025). A major psychotic disorder characterized by abnormalities in the perception or expression of reality.
brain glioblastoma (1 paper, 2020). A WHO grade IV malignant astrocytic tumor that arises from the brain, usually the cerebral hemispheres. "In a related study, KCNK1, KCNK3, and KCNK10 were significantly downregulated in brain glioblastoma (GBM)." (PMID 32906679, 2020).
thyroid cancer (1 paper, 2020). "However, KCNK1, KCNK6, KCNK7, KCNK9, KCNK10, KCNK13 and KCNK16 mRNA expressions were not related to the prognosis of patients with thyroid cancer." (PMID 32742463, 2020).
cancer (3 papers, 2017 to 2022). A tumor composed of atypical neoplastic, often pleomorphic cells that invade other tissues. "The data show that mRNA expression of KCNK1, KCNK7, and KCNK9 is upregulated in cancer tissues while KCNK2, KCNK3, KCNK5, KCNK10, KCNK13, KCNK15, and KCNK17 levels are decreased compared to controls." (PMID 31581133, 2019).
tumor (1 paper, 2019). "The data showed that mRNA levels of KCNK7, KCNK9 and KCNK10 correlated inversely with tumor differentiation degree." (PMID 31581133, 2019).
KCNK10 also shares sentences with these, for which no sentence is quoted: migraine (10 papers); ischemia (5); Cerebral ischemia (3); Anxiety (2); Hypoglycemia (2); mood disorder (2); Arrhythmia (1); autosomal dominant polycystic kidney disease (1); bipolar disorder (1); depression (1); glioblastoma (1); neurological diseases (1); papillary thyroid carcinoma (1); prediabetes (1); prostatitis (1); pulmonary arterial hypertension (1); rectum adenocarcinoma (1); Stroke (1).